IGFBP1 (insulin like growth factor binding protein 1)
Diseases named in the same sentence as IGFBP1 in open-access papers (continued):
Sharing a sentence is not in itself a finding about the gene and the disease.
endometriosis (continued). "Notably, exogenous BMP2 treatment restored the expression of the downregulated decidualization markers IGFBP1 and FOXO1 in both eutopic (endometriosis) ESCs and epithelial assembloids." (PMID 40072055, 2025). "Notably, PRMT5 overexpression restores IGFBP1 and PRL expression in eutopic ESCs of endometriosis patients, suggesting that PRMT5 dysregulation contributes to impaired decidualization in endometriosis." (PMID 40072055, 2025). "We applied strict criteria using eSF from patients with only endometriosis and no other uterine, pelvic or gynecologic disorders and those that show P4-resistance confirmed by microscopy and IGFBP1 assay." (PMID 32555663, 2020). "Further confirming the comprehensive disruption of P4 signaling in endometriosis, HOXA10, IGFBP1, PLZF, MIG-6, and CRISPLD2, all PGR targets implicated in endometrial function based on mouse studies, have been shown to be dysregulated in endometriosis patients." (PMID 31387263, 2019). "In addition, IGFBP-1 and PRL also show a lower secretion by cultured endometrial stromal cells from women with endometriosis than those from healthy women." (PMID 32063886, 2019). "In fact, ME-SFCs obtained from women with endometriosis exhibit significantly reduced IGFBP-1 expression in the absence of decidualization stimuli." (PMID 30134794, 2018). "Time course of IGFBP-1 secretion by vehicle- and 0.5 mM cAMP+ 1 μM MPA+ 10 nM E2-treated ME-derived SFCs isolated from endometriosis (Endo) and control subjects (n = 7 control, n = 7 endometriosis)." (PMID 30134794, 2018). "A difference in the production of IGFBP-1 was also confirmed in patients with both CE and endometriosis compared with the endometriosis patients without CE by western blotting (P < 0.05)." (PMID 28259137, 2017). "Additionally, the protein levels of IGFBP1 and PRL were reduced following transfection with mPRβ siRNA, confirming that mPRβ is essential for the decidualization process in cells from healthy women and women with endometriosis." (PMID 40806428, 2025). "In endometriosis FOXO1 was phosphorylated by the phosphatidylinositol 3 kinase (PI3K)/protein kinase B (AKT) signaling pathway and degraded by ubiquitination after exiting the nucleus, resulting in decreased expression of the downstream decidualization marker IGFBP1." (PMID 38795132, 2024). "However, PRMT5 supplementation obviously promoted IGFBP1 mRNA expression (31.56 vs. 91.18, P < 0.05) and secreted PRL levels (85.17 vs. 115.33 ng/mL, P < 0.001), indicating that PRMT5 rescued the decidualization defect of endometrial stromal cells from endometriosis patients." (PMID 36195592, 2022). "Our data shown that the significantly reduced protein level and mRNA expression of PRL and IGFBP-1 and the increase of cell number were oppositely observed in the CE patients compared with non-CE patients, no matter whether the patients have endometriosis or not." (PMID 28259137, 2017). "Interestingly, both inhibition of PI3K and AKT led to increasing nuclear FOXO1 and IGFBP1 levels in response to treatment with medroxyprogesterone acetate and dibutyryl cAMP, supporting evidence that the increased PI3K/AKT pathway is involved in the reduced decidual response in endometriosis." (PMID 24036443, 2013). "When only the samples with endometriosis were evaluated in the CE group (five patients) and the non-CE group (four patients), the mRNA levels of PRL and IGFBP-1 tended to be decreased in the CE group (P = 0.06 in both)." (PMID 28259137, 2017).
prostate carcinoma (22 papers, 2006 to 2025). A carcinoma that arises from epithelial cells of the prostate gland. "Men with higher IGF-II (1.06: 1.02, 1.11) and IGFBP-3 (1.08: 1.04, 1.11) had higher risks of overall prostate cancer, whereas higher IGFBP-1 was associated with a lower risk (0.95: 0.91, 0.99); these associations were attenuated following adjustment for IGF-I." (PMID 35726641, 2023). "A deeper look into the IGFBP1/IGFBP3 region revealed at least two independent signals of association with prostate cancer following the regional LD structure (excluding rs700752): one toward the IGFBP1 gene, and one encompassing the IGFBP3 gene." (PMID 27225428, 2016). "We have also detected associations of SNPs in IGFBP‐1/IGBP‐3 with prostate cancer aggressiveness which suggest a positive relationship with higher circulating IGF‐II and possibly IGFBP‐3 (this varies depending on the instrument used)." (PMID 27225428, 2016). "In prostate cancer, high level of IGFBP-1 was associated with increased cancer risk and a shorter time to castration resistant prostate cancer from androgen deprivation therapy (ADT) and reduced OS." (PMID 26217584, 2015). "It is known that alterations in the IGF axis, including a reduction in IGF-I and an increase in IGFBP-1, by lifestyle modification are associated with an in vitro reduction in prostate cancer cell (LNCaP) growth and increased apoptosis." (PMID 20885914, 2010). "An association between breast and prostate cancer and IGFBP1 has previously been reported." (PMID 35298474, 2022). "Raised BP may downregulate IGF‐binding protein‐1 (IGFBP‐1), and this might increase the risk of prostate cancer by increasing IGF‐1 activity." (PMID 34939344, 2022). "In addition, meta-analysis of published research investigating the association of IGF-1–IGF-2 and their binding proteins IGFBP-1–6 with prostate cancer confirmed that elevated circulating level of IGF-1 positively correlates with higher prostate cancer risk." (PMID 29487568, 2018). "We aimed to investigate the associations of IGF-I, IGF-II, IGFBP-1, IGFBP-2 and IGFBP-3 concentrations with overall, aggressive and early-onset prostate cancer." (PMID 35726641, 2023). "In our observational analyses, IGF-II, IGFBP-1 and IGFBP-3 were positively associated with overall prostate cancer, but we were underpowered to detect associations with aggressive or early-onset disease." (PMID 35726641, 2023). "Previous researches have revealed that the elevated expression of IGFBP1 is related to shorter time of metastasis and lower survival in gastric carcinoma and prostate cancer." (PMID 33282953, 2020). "This suggests that in prostate cancer, IGFBP-1 can both serve as a prognostic and predictive biomarker." (PMID 26217584, 2015). "IGFBP-1 binds with IGF-1, which increased the risk of prostate cancer and cardiometabolic diseases." (PMID 38575325, 2024). "Higher BMI is associated with lower concentrations of IGFBP-1 and IGFBP-2, which might lead to higher bioavailability of IGF-I, but evidence on the association of these binding proteins with prostate cancer mortality is very limited." (PMID 35509091, 2022). "On the other hand, this study found no or little evidence for the association of IGF-2, IGFBP-1, -2, and -3 with increased prostate cancer risk." (PMID 29487568, 2018). "No strong associations were observed for IGF-II, IGFBP-1 or IGFBP-2 with either milk intake or prostate cancer risk." (PMID 28361446, 2017). "In order to obtain a more complete picture of the IGFBP1/IGFBP3 genetic region and its relationship to prostate cancer, we carried out an analysis of all additional SNPs within these genes that were available in PRACTICAL (n = 39)." (PMID 27225428, 2016). "It should be noted that a different binding protein, IGFBP-1, which is responsible for shuttling IGF across capillary membranes into the target tissue, might be more predictive of prostate cancer risk, though concentrations were not measured in this study." (PMID 28417914, 2017).
prostate carcinoma (continued). "Whilst androgens did not correlate with the MMPs, ADAMS, ADAMTS, or IGF-1/IGFBP-1 in these subjects with PCOS, androgens may modulate MMPs in other clinical conditions, such as prostate cancer." (PMID 39796177, 2025).
metabolic syndrome (19 papers, 2011 to 2025). A cluster of metabolic risk factors for CARDIOVASCULAR DISEASES and TYPE 2 DIABETES MELLITUS. "Low IGFBP-1 is likely to be a useful early marker of metabolic syndrome, and, therefore, disease risk." (PMID 39595651, 2024). "Both IGFBP1 and 3 are related to insulin levels, fat accumulation, and have been linked to the metabolic syndrome, which also affects equids." (PMID 31022261, 2019). "A low level of IGFBP-1 is a marker for metabolic syndrome risk in both adults and children." (PMID 35586622, 2022). "AMPK phosphorylation, elevated uncoupling protein 1 (UCP1), and insulin-like growth factor binding protein 1 (IGFBP-1) protein levels in WAT in pu-erh tea also suggest its potential to modulate metabolic syndrome and improve WAT browning." (PMID 40647906, 2025). "In the presence of features of the metabolic syndrome, we recommend that IGFBP-1 be combined with other biomarkers and suggest that future research focuses on identifying the best combination." (PMID 39595651, 2024). "In a population cohort (n = 839, 40–65 y, 58% F), low IGFBP-1 (below the median) and high CRP (in the highest tertile) were together associated with a dramatic increase in the risk of metabolic syndrome (odds ratio 14)." (PMID 39595651, 2024). "Correlational analyses were performed relating circulating concentrations of IGFBP-1, anthropometric data, and indices of insulin sensitivity and dyslipidemia." (PMID 35586622, 2022). "Futhermore, patients with T2DM and low IGFBP1 levels (n = 17) had after 1 and 2 years still signs of the metabolic syndrome in contrast to the patients with T2DM and high IGFBP-1 (n = 11)." (PMID 32934313, 2020). "The simultaneous reduction in glucose, insulin, and IGF1 and the increase in IGFBP1 seen postoperatively, and remaining at follow-up, strengthen the possible reversibility of the metabolic syndrome coupled with PHPT." (PMID 24026893, 2013). "The inclusion of one or more pro-inflammatory cytokines that are associated with the metabolic syndrome, e.g., CRP, and/or likely to increase IGFBP-1 production, e.g., IL-6, could help in assessment at the individual level." (PMID 39595651, 2024). "Of note, semi-partial r values revealed that IGFBP-1 accounts for a greater fraction of the variance than body fatness for all indices of insulin sensitivity but not for indices of dyslipidemia risk, except for HDL cholesterol." (PMID 35586622, 2022). "The risk of having left ventricular hypertrophy (crude odds ratio) for the metabolic syndrome and its different components and insulin as well as physical activity, oestrogen and percentile levels of insulin-like growth factor binding protein-1 and insulin-like growth factor-1." (PMID 25461385, 2014). "Likewise, IGFBP-1 is recognized as an important regulator of glucose levels and a potential marker for the metabolic syndrome." (PMID 24548465, 2014). "Like IGFBP-1, a low fasting ghrelin level is a marker of the metabolic syndrome." (PMID 24555152, 2013). "Similarly, in the group with PreDM the subgroup with low IGFBP-1 levels (n = 32) at baseline had signs of the metabolic syndrome with decreased HDL and adiponectin as well as increased triglycerides, insulin, HOMA-IR and IGFSD compared to the subgroup with high IGFBP-1 (n = 13)." (PMID 32934313, 2020).
hepatocellular carcinoma (18 papers, 2015 to 2025). A malignant tumor that arises from hepatocytes. "IGFBP1 acts as a proangiogenic factor contributing to HCV-associated with hepatocellular carcinoma pathogenesis and that elevated IGFBP1 expression is associated with hematogenous metastasis and poor outcome of gastric cancer." (PMID 34066023, 2021). "Recent studies have shown that IGFBP1 enhances resistance to anti‐angiogenic TKIs in hepatocellular carcinoma." (PMID 40052383, 2025). "In hepatomas, the increased expression of insulin-like growth factor receptor (IGFR) is correlated with the stimulation of cancer cell proliferation, survival and migration, and the decreased expression of IGFBP1 enhances the hepatoma cell invasion process." (PMID 37298551, 2023). "IGFBP1 has also acted as a tumor inhibitor in hepatocellular cancer through downregulation of the MMP expression." (PMID 33282953, 2020). "IGFBP-1 is a hepatocyte-derived secreted protein that undergoes various phosphorylation events and localizes to the nucleus and/or cytoplasm in hepatocellular carcinoma." (PMID 28143425, 2017). "These authors also demonstrated that amino acid restriction increased the abundance of IGFBP-1 mRNA in rat hepatoma cells, stressing the importance of both insulin and protein substrate in the regulation of IGFBP-1." (PMID 25909895, 2015). "For instance, in hepatocellular carcinoma, IGFBP1 acts as an inhibitor of IGF-1R pathway signaling." (PMID 41488652, 2025). "Therefore, we exogenously overexpressed HBP1 in human hepatocellular carcinoma-derived HepG2 cells, PLC hepatoma cells, and normal liver L02 cells, and this increased both the protein and mRNA expression of IGFBP1 in all three cell lines." (PMID 36326689, 2022). "IGFBP1 gene expression has also became undetectable in rapidly proliferating hepatoma cells." (PMID 29702590, 2018). "IGFBP1 participates in cellular invasion process of human hepatoma cells lines." (PMID 29702590, 2018). "IGFBP-1 is an early-response factor rapidly induced by glucocorticoids, pro-inflammatory cytokines and ROS as well as other stress-related events with hepatic IGFBP-1 mRNA expression being also increased in alcoholic liver disease, cirrhosis, hepatocellular carcinomas and steatosis." (PMID 29296203, 2017). "In hepatocellular carcinoma (HCC), decreased expression of IGFBP1 is correlated with microvascular invasion and metastasis." (PMID 28880250, 2017). "The regulation of IGFBP1 and FOXO3 revealed a novel mechanism in the ursolic acid-induced inhibition of hepatocellular carcinoma cell growth." (PMID 39334758, 2024). "Gong et al21 have found that inhibition of FASN in hepatocellular carcinoma cell lines reduces the migration and invasion by reducing the HIF‐1α/IGFBP1 pathway." (PMID 33164330, 2020). "The expression of genes encoding proteins known to be associated with the cell cycle (E2F1), adhesion and proteolysis (OPCML) and hepatocellular carcinoma (FZD7, IGFBP1 and LEF1) was elevated 3- to 9-fold." (PMID 26442469, 2015).
gastric cancer (14 papers, 2020 to 2024). A primary or metastatic malignant neoplasm involving the stomach. "High insulin‐like growth factor binding protein 1 (IGFBP1) expression is significantly associated with poorer survival and relapse‐free survival in patients with gastric cancer." (PMID 39233332, 2024). "Stomach adenocarcinoma (STAD) and gastric cancer had more IGFBP1–7 mutations than other tumor types." (PMID 34745945, 2021). "IGFBP1/5/7 expression was significantly associated with overall survival whereas IGFBP6/7 expression was significantly correlated with disease-free survival in gastric cancer patients." (PMID 34745945, 2021). "STAD and gastric cancer had the most IGFBP1–7 mutations compared with other tumors." (PMID 34745945, 2021). "In vitro and in vivo experiments validate that IGFBP1 facilitates enhanced adaptation of stomach cancer cells to endoplasmic reticulum contingency." (PMID 38700505, 2024). "We have confirmed that IGFBP1 promotes the malignant phenotype of stomach cancer, including proliferation, anti-apoptosis, invasion, and migration." (PMID 38700505, 2024). "IGFBP1’s role in enhancing cancer cell adaptation to endoplasmic reticulum stress suggests its importance in stomach cancer prognosis and treatment." (PMID 38700505, 2024). "Taken together, this study we conducted in vitro found that IGFBP1 is capable of proliferating, invasive and migrating stomach cancer cells in a proliferation-like manner." (PMID 38700505, 2024). "In contrast, the experimental group showed fewer nodules and cancer cells, suggesting that IGFBP1 promotes gastric cancer metastasis." (PMID 38700505, 2024). "The gene IGFBP1, which had the highest weight coefficient in the prognostic signature, was found to promote the malignant phenotype of stomach cancer cells, suggesting its potential as a therapeutic target." (PMID 38700505, 2024). "As a key component of the UPR prognostic signature, IGFBP1 serves as an independent prognostic factor for poor stomach cancer outcomes." (PMID 38700505, 2024). "To further investigate the impact of IGFBP1 on the metastatic capability of gastric cancer, we injected the blank control group (shNC) and the stable IGFBP1-knockdown cell line (shIGFBP1 group) into nude mice via tail vein." (PMID 38700505, 2024). "These animal experiments demonstrate that IGFBP1 not only enhances ER adaptability but also promotes gastric cancer progression, thereby nominating IGFBP1 as a potential therapeutic target for gastric cancer." (PMID 38700505, 2024). "To validate this observation, we overexpressed IGFBP1 in another gastric cancer cell line with relatively low IGFBP1 expression, HGC-27, and treated with Tunicamycin to induce ER stress." (PMID 38700505, 2024). "It has been demonstrated in vitro experiment that the IGFBP1 promotes the malignant phenotype of stomach cancer, including proliferation, invasion, and migration." (PMID 38700505, 2024). "Then, using the stomach cancer cell lines MKN45 and AGS, we performed loss-of-function experiments and silenced expression of IGFBP1 to investigate its biological function." (PMID 38700505, 2024). "With collection of the gene expression data of cancer vs. normal patients, tumor vs. adjacent tumor tissue, and IGFBP mutations in all cancer types and immune infiltration data, we provided a relative complete analysis for IGFBP1–7 in gastric cancer." (PMID 34745945, 2021). "Expression levels of IGFBP3, IGFBP4, and IGFBP7 were significantly elevated in gastric cancer tissues, whereas those of IGFBP1 were reduced in normal tissues." (PMID 34745945, 2021). "Our study focused on the prognostic value of IGFBP1–6 in gastric cancer; however, IGFBP7 is also significantly upregulated in STAD patients and closely related to prognosis." (PMID 34745945, 2021).